POP1 (POP1 ribonuclease P/MRP subunit)
Description:
Component of ribonuclease P, a ribonucleoprotein complex that generates mature tRNA molecules by cleaving their 5'-ends. Also a component of the MRP ribonuclease complex, which cleaves pre-rRNA sequences.
Synonyms: ANXD2
Tractability: PROTAC: ubiquitination databases record sites on it; its protein half-life has been measured.
Gene: Protein-coding gene on chromosome 8 (98,117,293 to 98,159,835, forward strand). Ensembl gene ENSG00000104356.
Subcellular location: Nucleus, nucleolus
Subcellular location (Human Protein Atlas): Nucleoli
Pathways (Reactome):
Metabolism of RNA: tRNA processing in the nucleus
Gene Ontology:
Molecular function: protein binding; ribonuclease P activity; ribonuclease P RNA binding; RNA binding
Biological process: tRNA 5'-leader removal; tRNA decay; RNA processing; tRNA processing
Cellular component: extracellular region; multimeric ribonuclease P complex; nucleolar ribonuclease P complex; nucleolus; ribonuclease MRP complex; nucleoplasm; nucleus
Genetic constraint (gnomAD): Loss-of-function variants: 71 observed, 105.02 expected, observed/expected ratio (o/e) 0.68, 90% interval 0.56 to 0.82. The upper end of that interval is the gene's LOEUF score, 0.82, which puts it in group 3 of 6, group 1 being the genes least tolerant of losing a copy. Missense variants: 1,104 observed, 1,317.7 expected, observed/expected ratio (o/e) 0.84, 90% interval 0.8 to 0.88. Synonymous variants: 434 observed, 483.87 expected, observed/expected ratio (o/e) 0.9, 90% interval 0.83 to 0.97.
Homologues: Orthologues: chimpanzee POP1 (99% identical), macaque POP1 (96% identical), dog POP1 (83% identical), rabbit POP1 (83% identical), pig POP1 (82% identical), guinea pig POP1 (81% identical), rat Pop1 (78% identical), mouse Pop1 (77% identical), tropical clawed frog pop1 (54% identical), Drosophila melanogaster Pop1 (25% identical), zebrafish pop1 (23% identical), Caenorhabditis elegans popl-1 (18% identical). Paralogues in human: SERAC1 (13% identical).
Diseases named in the same sentence as POP1 in open-access papers:
POP1 is named in the same sentence as 26 diseases in open-access papers, as found by Europe PMC text mining. Sharing a sentence is not in itself a finding about the gene and the disease. The quoted sentences say what the papers report.
breast carcinoma (6 papers, 2021 to 2024). "Oval all, we identified three RBP-coding genes (MRPL12, MRPL13 and POP1) that functioned as risk factors and independent prognostic factors for breast cancer." (PMID 34322380, 2021). "By examining mRNA and protein expression levels of POP1 in 8 breast cancer cell lines containing different subtypes and tissue samples from 26 patients, we determined that POP1 was significantly up-regulated in TNBC." (PMID 39268503, 2024). "Mutations in RMRP promotor have been correlated with breast cancer and POP1 has been identified as part of a prognostic signature in breast cancer." (PMID 36192788, 2022). "All these results suggested that MRPL12, MRPL13 and POP1 should be designed as biomarkers and potential intervening targets for breast cancer." (PMID 34322380, 2021). "In brief, majority of patients with abundant POP1 expression showed poorer survival probability, and silencing the endogenous POP1 dramatically suppressed the viability and metastatic ability of breast cancer cells." (PMID 34322380, 2021). "Although MRPL12, MRPL13 or POP1 were over-expressed in tumor tissues, there were also some slight differences in expression pattern between each subtype of breast cancer, wherein TNBC cases tolerated the highest expression of these three RBPs." (PMID 34322380, 2021). "MRPL12, MRPL13 and POP1 might act as oncogenes in maintaining cellular viability and accelerating metastasis of breast cancer cells, implying the possibility of which to be designed as biomarkers and/or therapeutic targets for breast cancer." (PMID 34322380, 2021). "Moreover, analogous to MRPL12 and MRPL13, our results also revealed that POP1 functioned as an oncogene in breast cancer." (PMID 34322380, 2021). "Moreover, the downregulation of endogenous MRPL12, MRPL13, or POP1 expression could significantly inhibit the viability and migration of breast cancer cells in vitro." (PMID 35719986, 2022). "All these results confirmed that MRPL12, MRPL13 and POP1 acted as oncogenes in breast cancer cells, therefore, they might be regarded as prognostic indicators in breast cancer, but also could be designed as therapeutic targets of breast cancer." (PMID 34322380, 2021). "Furthermore, we performed some preliminary experiments and provided concrete evidence that MRPL12, MRPL13 and POP1 might be oncogenes in maintaining cellular viability as well as accelerating metastasis of the breast cancer cells." (PMID 34322380, 2021). "Furthermore, experimental validations showed that down-regulating the expression of endogenous MRPL12, MRPL13 or POP1 could dramatically suppress the cellular viability and migration of breast cancer cells in vitro." (PMID 34322380, 2021). "These authors concluded that MRPL12, MRPL13, and POP1 might act as oncogenes in maintaining cellular viability and stimulating the metastasis of breast cancer cells, involving the possibility of their being designed as biomarkers and/or therapeutic targets for breast cancer." (PMID 37298568, 2023). "In breast cancer, a three-gene prognostic model based on MRPL12, MRPL13, and POP1 has significant predictive value for survival." (PMID 35719986, 2022). "NOP14/MRPS23/POP1 exhibit prognostic value in colorectal cancer, while APOBEC3C/DCAF13/EIF4E3/EZR possess significance in predicting prognosis of breast cancer." (PMID 34322380, 2021). "All these results indicated that MRPL12, MRPL13 and POP1 not only could be designed as prognostic factors for predicting survival probability of patients with breast cancer, but also could be used as potential targets for clinical intervention of breast cancer." (PMID 34322380, 2021). "Notably, by reviewing the Comparative Toxicogenomics Database (CTD), we excavated three available compounds (Acetaminophen, Urethane and Tunicamycin), which could inhibit the MRPL12, MRPL13 and POP1 simultaneously, implying their anti-neoplastic effects on breast cancer." (PMID 34322380, 2021).
breast carcinoma (continued). "In addition, the expression pattern of MRPL12, MRPL13 or POP1 were significantly associated with tumor stage, suggesting that these three RBP-coding genes could be regarded as potential biomarkers for breast cancer prognosis." (PMID 34322380, 2021). "Besides, some compounds (such as the Acetaminophen, Urethane and Tunicamycin) were predicted for curing breast cancer via targeting MRPL12, MRPL13 and POP1 simultaneously." (PMID 34322380, 2021). "Furthermore, down-regulating the expression of endogenous MRPL12, MRPL13 or POP1 in breast cancer cells, resulted in dramatically suppression of cellular viability and migration, suggesting that these three RBP-coding genes might act as oncogenes in accelerating the progress of breast cancer." (PMID 34322380, 2021).
Sepsis (2 papers, 2020 to 2022). Sepsis is defined as life-threatening organ dysfunction caused by a dysregulated host response to infection. "Cell-penetrating peptides are frequently employed for the delivery of molecules targeting intracellular signaling pathways and we previously demonstrated that cell penetrating POP1 is able to ameliorate sepsis." (PMID 36225929, 2022). "For instance, CAPS and sepsis patients have significantly less POP1 expression in whole blood than healthy controls, POP1, POP2, and CARD18 are downregulated in periodontal disease and CARD18 is highly expressed in the epidermis, but expression is lost in lichen planus." (PMID 32962268, 2020).
systemic sclerosis (2 papers, 2021 to 2022). A chronic disorder, possibly autoimmune, marked by excessive production of collagen which results in hardening and thickening of body tissues. "Interestingly, hRpp38 has been identified as the main component, along with Pop1, Rpp25 and Rpp30, of the Th/To autoantigen present in the sera of patients suffering from systemic sclerosis scleroderma (SSc)." (PMID 34638646, 2021).
anauxetic dysplasia (1 paper, 2024). A spondyloepimetaphyseal dysplasia that is characterized by the prenatal onset of extreme short stature, an adult height of less than 85 cm, hypodontia, and mild mental retardation. "Documented mutations in POP1 cause Anauxetic Dysplasia with pathognomonic short stature, hypoplastic midface and hypodontia along with mild intellectual disability." (PMID 38448444, 2024).
Arrhythmia (1 paper, 2014). Any cardiac rhythm other than the normal sinus rhythm. "L2 larvae homozygous for the pop-1(hu9) and pop-1(q645) alleles had a 11–18% increase in mean cycle time and greater arrhythmia than N2 controls." (PMID 24516405, 2014).
cervical cancer (1 paper, 2023). A primary or metastatic malignant neoplasm involving the cervix. "The effects of purslane polysaccharide (POP1) and its five sulfated derivatives (POP1-s1, POP1-s2, POP1-s3, POP1-s4 and POP1-s5) on the human hepatoma cell line (HepG2) and cervical cancer cell line (Hela) were reported." (PMID 37375369, 2023).
COVID-19 (1 paper, 2022). A disease caused by infection with severe acute respiratory syndrome coronavirus 2. "COVID-19 patients were older than HLH patients for both POP1 and POP2, but there were similar proportions of males and females across COVID-19 and HLH." (PMID 36589196, 2022). "Modified HScores were significantly (p<0.0001) higher for HLH patients than COVID-19 patients for POP1 (HLH, 190.5±46.8; COVID-19, 132.8±40.1) and POP2 (HLH, 97.6±47.9; COVID-19, 38.0±26.8)." (PMID 36589196, 2022). "It is important to clarify that our modified HScore for POP1 did not include hemophagocytosis and therefore yielded lower than expected mean scores for both our COVID-19 patients (132.8±40.1) and HLH patients (190.5±46.8)." (PMID 36589196, 2022).
endometrial cancer (1 paper, 2024). Primary or metastatic malignant neoplasm involving the endometrium (mucous membrane that lines the endometrial cavity). "In addition, POP1 mutations were identified at high frequencies in esophagogastric cancer, endometrial cancer, melanoma, and CRC and were especially prominent in endometrial cancer (7.00% of 586 cases)." (PMID 38862431, 2024). "Amplification of POP1 and RPP29 was frequently observed, such as in ovarian epithelial tumors and endometrial cancer; these RNase P subunits may have particular roles in the promotion of tumorigenesis and could subsequently be developed as potential prognostic markers." (PMID 38862431, 2024).
gout (1 paper, 2022). A condition characterized by painful swelling of the joints, which is caused by deposition of urate crystals. "Since, POP1TG mice were protected from gout, we utilized cell penetrating POP1 to investigate its efficacy for the treatment of gout in a proof-of-principle study." (PMID 36225929, 2022). "Here we demonstrate that POP1 expression in macrophages is sufficient to dampen MSU crystal-mediated inflammatory responses in animal models of gout." (PMID 36225929, 2022). "Overall, we demonstrate that POP1 may play a crucial role in regulating inflammatory responses in gout." (PMID 36225929, 2022). "While POP1 specifically prevents inflammasome-mediated cytokine release in isolated mouse macrophages, a broader inhibition of pro-inflammatory cytokines and chemokines was observed in the in vivo gout model." (PMID 36225929, 2022). "Since POP1 expression in mice that otherwise lack POP1 ameliorated gout, it is conceivable that dysregulated expression of POP1 may affect the susceptibility for developing gout flares." (PMID 36225929, 2022). "Here we show that POP1 inhibits uric acid crystal-induced NLRP3 inflammasome activation, inflammation and ameliorates gout in a mouse model." (PMID 36225929, 2022). "We identified that reminiscent to POP2, also POP1 inhibits uric acid crystal-induced NLRP3 inflammasome activation and ameliorates gout." (PMID 36225929, 2022). "We previously showed that POP2 interferes with MSU crystal induced inflammasome responses and ameliorates gout, but the role of POP1 in the pathology of gout has not been investigated yet." (PMID 36225929, 2022).
Hyperglycemia (1 paper, 2018). An increased concentration of glucose in the blood. "Beneficial effects of Olaparib on lifespan were also ablated by feeding RNAi knock-down of the TCF7L2 homolog, pop-1, suggesting that TCF7L2 is required to gain therapeutic benefit from PARP-1 inhibition in the context of hyperglycemia." (PMID 29392078, 2018).
immunosuppression (1 paper, 2024). "These outcomes indicate that POP-1 supplementation altered the gut microbiota and produced different metabolites vital in regulating immunosuppression disease." (PMID 39272445, 2024).
Obesity (1 paper, 2021). Accumulation of substantial excess body fat. "In support of this notion, expression of Tcf7l2 in mice and TCF7L2 in humans negatively correlates with BMI, which is in line with our observation that knockdown of pop-1 promotes obesity in C. elegans." (PMID 34492009, 2021).
prostate carcinoma (1 paper, 2020). A carcinoma that arises from epithelial cells of the prostate gland. "In a previous study, POP1 was found to be enriched in human prostate cancer cell lines, suggesting that it may be suitable as a potential marker for the diagnosis and prognosis of prostate cancer." (PMID 32828126, 2020).
schistosomiasis (1 paper, 2015). An infectious disease caused by parasitic trematodes of the genus Schistosoma that colonize human blood vessels and release eggs that can cause granulomatous reactions leading to acute (swimmer's itch or acute schistosomiasis syndrome) or chronic disease. "Of the seven modes of prevalence variation, we focused on the sustained modes (i.e., POP1 and POP2) as measured by the corresponding e-folding time (e-folding > a quarter of period) when interpreting the space-time dynamics of schistosomiasis." (PMID 25881189, 2015).
cancer (7 papers, 2020 to 2026). A tumor composed of atypical neoplastic, often pleomorphic cells that invade other tissues. "First, mutation analysis of the TCGA pan-cancer cohort revealed that POP1 mutation frequency in BC ranked fourth among all tumor types." (PMID 36084948, 2022). "Thus, sulfonated treatment of native POP1 can enhance its cytotoxicity against tumor cells, and sulfate derivatives of POP1 will play an auxiliary role alongside anticancer drugs in future cancer therapies." (PMID 37375369, 2023). "Some identified prognostic DE RBPs have not been associated with cancers, such as CELF4, POP1, TDRD6, TDRD7, LRRFIP2, and ZC3H12C." (PMID 33224957, 2020).
tumor (7 papers, 2018 to 2025). "Mutation analysis showed that POP1 mutation frequency in BC was the fourth among all tumor types." (PMID 36084948, 2022). "The results of tumor formation experiment in nude mice showed that overexpression of CDKN1A or treatment with STM2457 in cells with high POP1 expression greatly impaired the tumor formation ability." (PMID 39268503, 2024). "A recent study showed that similar to its function in yeast, POP1 also promotes tumor progression in human tumors by keeping telomeres intact." (PMID 39268503, 2024). "POP1-s3 showed the most obvious inhibitory effect; in particular, at a concentration of 2000 μg/mL, its inhibitory activity was the highest, reaching 51.3 ± 1.3%, indicating that sulfate modification can enhance the cytotoxicity of POP1 to tumor cells." (PMID 37375369, 2023). "Exploring the relationship between POP1 and the tumor immune microenvironment can contribute to a stronger indicator of tumor status and prediction of treatment response and efficacy." (PMID 36084948, 2022). "At present, the role of POP1 in anti-tumor immunity is rarely studied." (PMID 36084948, 2022). "The collected tumor photograph and tumor growth curves showed that overexpression of POP1 promoted the growth of TNBC cells, while knockdown of POP1 impaired the tumorigenic ability in vivo." (PMID 39268503, 2024).
infection (3 papers, 2017 to 2025). The state of being infected such as from the introduction of a foreign agent such as serum, vaccine, antigenic substance or organism. "The infection percentage in F2-generation of pop1 showed partial dominance towards susceptibility, and absence of dominance in the other base population." (PMID 35736689, 2022). "The correlated response was −14.87 and −11.76% for HFC, 40.95 and 24.62 for LFZ, 20.64 and 14.23% for NCP−1, 22.13 and 14.23% for SYP−1, and −20.77 and −9.17% from the mid-parent for infection% in pop1 and pop2, respectively." (PMID 35736689, 2022). "The correlated observed gain in infection% was significant (p ≤0.01) from the mid-parent, and ranged from −20.77 to −27.32% in pop1, and from −7.02 to −11.58% in pop2." (PMID 35736689, 2022). "Selection for SYP−1 significantly (p ≤ 0.01) decreased infection%, by −25.16 and −10.04% from the mid-parent in pop1 and pop2, respectively." (PMID 35736689, 2022). "Selection for earliness improved HFC by −14.74 and −11.76%, and infection % by −25.16 and −8.49% from the mid-parent for pop1 and pop2, respectively." (PMID 35736689, 2022). "Selection for LFZ showed a favorable significant indirect response from the mid-parent for NCP−1 (13.73% **, 17.13% **, SYP−1 (19.51% **, 16.28% **), and infection % (−26.61% **, −11.58% **) in pop1 and pop2, respectively." (PMID 35736689, 2022). "The favorable significant indirect response for NCP−1 was 13.73 and 17.11%, 19.51 and 16.28% for SYP−1, and −26.61 and−11.58% for infection % from the mid-parent in pop1 and pop2, respectively." (PMID 35736689, 2022). "Furthermore, a significant (p ≤ 0.01) reduction in infection% from the mid-parent of −22.67 and −10.04% in pop1 and pop2, respectively, was obtained." (PMID 35736689, 2022). "Selection for LFZR was the best out of the eight methods for improving LFZ (30.83% **, 24.94% **), SYP−1 (34.04% **, 28.53% **) infection %, and HFC (−15.13% *, −12.03%) from the mid-parent in pop1 and pop2, respectively." (PMID 35736689, 2022). "Notably, during the chronic phase of the infection, pop1 cannot retain its functionality, irrespective of its origin, which may hamper its ability to control reactivation." (PMID 39975082, 2025).
connective tissue disease (2 papers, 2021 to 2024). "In patients with connective tissue disease, POP1 is also an autoantigen and suppresses inflammation." (PMID 39628476, 2024). "Interestingly, Pop1 was isolated as an autoantigen in patients suffering from connective tissue diseases, suggesting possible additional roles for Pop1." (PMID 34638646, 2021).
skeletal dysplasia (1 paper, 2021). Any Mendelian diseases that affects growth and development of the skeleton. "Biallelic mutation or haploinsufficiency of POP1 impairs the holoenzyme assembly and results in a severe skeletal dysplasia, but whether it is involved in tumorigenesis still is unsubstantiated." (PMID 34322380, 2021).
POP1 also shares sentences with these, for which no sentence is quoted: colorectal cancer (1 paper); gastric cancer (1); Hemophagocytosis (1); hepatoma (1); lichen planus (1); myeloma (1); periodontal disease (1).